KMT2D (lysine methyltransferase 2D)
Diseases named in the same sentence as KMT2D in open-access papers (continued):
Sharing a sentence is not in itself a finding about the gene and the disease.
T cell lymphoma (3 papers, 2022 to 2024). "MLL2 (also known as KMT2D) is mutated in angioimmunoblastic T-cell lymphoma (AITL), PTCL not otherwise specified (PTCL-NOS), DLBCL, FL, and NK/T-cell lymphoma (NK/TCL), where approximately 91% of mutations result in silencing its histone methylation function." (PMID 35326620, 2022). "In fact, the combination of chidamide and decitabine improves the KMT2D-PU.1 transcription factor interaction, which inactivates the MAPK pathway, constitutively activated in T-cell lymphoma." (PMID 35326620, 2022).
triple-negative breast carcinoma (3 papers, 2021 to 2024). An invasive breast carcinoma which is negative for expression of estrogen receptor (ER), progesterone receptor (PR), and human epidermal growth factor receptor 2 (HER2). "KMT2C and KMT2D, encoding histone H3 lysine 4 methyltransferases, are among the most commonly mutated genes in triple-negative breast cancer (TNBC)." (PMID 38926506, 2024).
viral infections (3 papers, 2023). "The enrichment analysis of its target genes also indicated that miR-346 is deeply associated with pathways related to viral infections and malignancies; therefore, we further studied its target hub gene, KMT2D." (PMID 36841815, 2023). "Targeting the KDM6A/KMT2D/p300 axis offers several potential advantages in the regulation of receptor expression and diverse virus infection." (PMID 37410700, 2023). "For the genes with cis-regulatory DRE in viral infections, Ctps and Tent5c served as the critical signal factors in lymphocyte proliferation and Kmt2d regulates CD8 T cell development and differentiation." (PMID 37081881, 2023). "We next sought to define the potential role for KMT2D and EP300 in viral infection and receptor expression." (PMID 37410700, 2023). "We next directly interrogated the role of KMT2D and EP300 in viral infection." (PMID 37410700, 2023).
22q11.2 deletion syndrome (2 papers, 2020 to 2021). 22q11.2 deletion syndrome (DS) is a chromosomal anomaly which causes a congenital malformation disorder whose common features include cardiac defects, palatal anomalies, facial dysmorphism, developmental delay and immune deficiency. "DiGeorge syndrome (del22q11) was most common, followed by mutations in CTLA4, RMRP, IKZF1, and KMT2D." (PMID 33968040, 2021).
ameloblastoma (2 papers, 2021 to 2025). The most common odontogenic tumor, arising from the epithelial component of the embryonic tooth and usually affecting the molar-ramus region of the mandible or maxilla. "Additional studies showed gene expression profile differences between plexiform and follicular ameloblastomas, with follicular ameloblastomas expressing variants of BRAF, KMT2D, and ABL1, while plexiform ameloblastomas expressed variants of ALK, BRAF, KRAS, KMT2D, SMO, KMT2A, and BRCA2." (PMID 38607614, 2025).
bladder tumors (2 papers, 2018 to 2023). "KMT2D is a known tumor suppressor that is mutated in a quarter of bladder tumors and also regulates gene transcription." (PMID 30176882, 2018). "No mutations in a known oncogene or tumor suppressor gene are shared by all three tumors; however, the primary bladder tumor and the lung metastasis share known oncogenic mutations frequently found in bladder tumors, such as mutations in the KMT2D and RXRA genes." (PMID 30176882, 2018).
carcinoma in situ (2 papers, 2023 to 2025). "When combined with deletion of Kmt2c and/or Kmt2d, the bladder urothelium exhibited dysplasia that progressed to nuclear pleomorphism and abnormal mitoses fulfilling the criteria of carcinoma in situ (CIS) in some mice." (PMID 39806204, 2025).
esophageal cancer (2 papers, 2022 to 2025). A primary or metastatic malignant neoplasm involving the esophagus. "Our findings suggest that hsa_circ_0000977 may also promote the progression of esophageal cancer through the hsa_circ_0000977/miR‐874‐3p/KMT2D axis." (PMID 35476874, 2022).
Fanconi anemia (2 papers, 2023 to 2024). Fanconi anemia (FA) is a hereditary DNA repair disorder characterized by progressive pancytopenia with bone marrow failure, variable congenital malformations and predisposition to develop hematological or solid tumors. "Here, the authors show that KMT2D deficiency in HNSCC impairs the Fanconi Anemia (FA)/BRCA pathway under glycolytic inhibition, rendering HNSCC hypersensitive to DNA crosslinking agents and PARP inhibitors." (PMID 39117659, 2024). "Additionally, KMT2D loss decreases the expression of Fanconi Anemia (FA)/BRCA pathway genes under glycolytic inhibition." (PMID 39117659, 2024).
goblet cell adenocarcinomas (2 papers, 2023). "KDM6A and KMT2D mutations have been reported in the appendiceal goblet cell carcinoid, mixed goblet cell carcinoid–adenocarcinoma, and some appendiceal mucinous adenocarcinomas and adenocarcinomas." (PMID 37566041, 2023). "Most of these mutations were also identified in other studies; for example, mutations in KDM6A, KMT2D, SMARCA4, and ARID1A have been previously reported not only in appendiceal adenocarcinomas but also in appendiceal goblet cell carcinomas." (PMID 37566041, 2023).
liver cancer (2 papers, 2023 to 2025). An epithelial or non-epithelial malignant neoplasm that arises from the liver. "Notably, HCC also harbors mutations in KMT2D, while KDM6A/UTX, an H3K27 demethylase within the COMPASS-like complex, has been functionally established as a potent tumor suppressor in pancreatic and liver cancers." (PMID 37261974, 2023).
lung squamous cell carcinoma (2 papers, 2020 to 2024). "Deficiency of KMT2D drives sensitivity of lung squamous cell carcinoma to RTK–RAS inhibition." (PMID 39564571, 2024).
MALT lymphoma (2 papers, 2021). An indolent, extranodal type of non-Hodgkin lymphoma composed of small B-lymphocytes (centrocyte-like cells). "Conversely, NMZLs display an inactivation of PTPRD (14% in NMZLs vs. 3% in MALT lymphomas) and a much higher prevalence of mutations affecting KMT2D (34% in NMZL vs. 15% in MALT lymphomas)." (PMID 34590593, 2021). "Inactivation of chromatin remodeling genes are frequently observed in MALT lymphomas, with the most common mutated genes being TET2, KMT2D, CREBBP, TBL1X1, KMT2C, MT2C, EP300, among others." (PMID 35008340, 2021). "In OAMZL, the most commonly reported epigenetic mutated gene is KMT2D with frequencies varying from 14% to 22%, and in Helicobacter pylori-negative gastric MALT lymphoma, KMT2D (17%) and CREBBP (14%) are the two most epigenetic regulator gene mutations." (PMID 35008340, 2021).
myeloid malignancies (2 papers, 2023). "Other histone methylating genes, such as KMT5B/EZH1/KMT2D/KMT2E/SETD5, were also included in brown module, and related to pathological process or prognosis of myeloid neoplasms (MDS/AML)." (PMID 37953918, 2023).
myocardial ischemia (2 papers, 2022 to 2023). A disorder of cardiac function caused by insufficient blood flow to the muscle tissue of the heart. "Therefore, we cultured H9C2 cells in serum-free DMEM medium to mimic the state of nutrient loss after acute myocardial ischemia and to determine the expression of Rasd1 and Kmt2d in the H9C2 cells." (PMID 35938163, 2022). "In this study, cardiomyocyte-specific KMT2D knockout (KMT2D-cKO) and control (KMT2D-Ctl) mice were exposed to sham or myocardial ischemia (MI) surgery." (PMID 35938163, 2022). "This study suggests that the strategy of targeting KMT2D could be a potential therapeutic approach for angiogenesis against myocardial ischemia and heart failure." (PMID 36947365, 2023).
nasopharyngeal carcinoma (2 papers, 2022 to 2025). A carcinoma arising from the nasopharyngeal epithelium. "Higher frequencies in primary mutations of the KMT2D gene have been highlighted in the literature including studies related to the mutational landscape of primary nasopharyngeal carcinomas and oropharyngeal cancers." (PMID 41590495, 2025).
paraganglioma (2 papers, 2017 to 2019). A benign or malignant neoplasm arising from paraganglia located along the sympathetic or parasympathetic nerves.
prostate adenocarcinoma (2 papers, 2023 to 2025). "Although the exact roles of these genes in NEPC development remain to be elucidated, some of them (i.e., TTN, MUC16, and KMT2D) are reportedly associated with disease progression and treatment resistance in prostate adenocarcinoma and other types of cancers." (PMID 37025467, 2023).
schizophrenia (2 papers, 2021 to 2025). A major psychotic disorder characterized by abnormalities in the perception or expression of reality. "In addition to including members of the Set1-like H3K4 methyltransferase family (Kmt2a, Kmt2b, Kmt2c, and Kmt2d), these modules also encompassed rare variant genes associated with schizophrenia and ASD (Setd1a, Cacna1g, Ank3, Shank1, and Shank3)." (PMID 40102613, 2025).
acute leukemia (1 paper, 2025). A clonal (malignant) hematopoietic disorder with an acute onset, affecting the bone marrow and the peripheral blood. "In acute leukemia (AML), KMT2D has been demonstrated to regulate ribosomal biogenesis by modulating the mTOR signaling pathway, thereby influencing tumorigenesis and progression." (PMID 41372946, 2025).
acute lymphoblastic leukemia (1 paper, 2024). Leukemia with an acute onset, characterized by the presence of lymphoblasts in the bone marrow and the peripheral blood. "However, a comprehensive study of epigenetic landscapes in acute lymphoblastic leukemia (ALL) found no role for KMT2D mutations in GC resistance-associated chromatin accessibility changes." (PMID 39025450, 2024).
adamantinoma (1 paper, 2025). A low grade malignant neoplasm arising from the long bones. "The application of WES and RNA sequencing (RNA‐Seq) on both tumor types resulted in the recurrent mutation of Lysine Methyltransferase 2D (KMT2D) gene in 38% of adamantinomas, indicating the potential role of chromatin structure and integrity in adamantinoma carcinogenesis." (PMID 40249565, 2025).
albinism (1 paper, 2020). A congenital disorder characterized by partial or complete absence of melanin pigment in the eyes, hair, or skin. "The genes identified for MAC were KMT2D, MAB2IL2, ALDH1A3; ASDA were KERA, PAX6, MYOC, TGFBI, and SLC4A11; congenital cataract were CRYBB2, EPHA2, HSF4 and BCOR; infantile nystagmus were CACNA1A and FRMD7; and albinism were OCA2, GPR143, HPS6 and SLC38A8." (PMID 32830442, 2020).
anaplastic thyroid carcinomas (1 paper, 2021). "In fact, histone methyltransferase genes (KMT2A, KMT2C, KMT2D, and SETD2) are increasingly impaired in poorly differentiated and anaplastic thyroid carcinomas." (PMID 33543394, 2021).
and soft-tissue tumors (1 paper, 2023). "Along the same lines, KMT2D would, if being a genuine tumor predisposition gene (TPG), predispose to a rather wide range of malignancies including bone- and soft-tissue tumors, hematological malignancies, embryonal tumors and carcinoma’s." (PMID 35856126, 2023).
Anxiety (1 paper, 2022). Intense feelings of nervousness, tension, or panic often arise in response to interpersonal stresses. "Anxiety scores from children possessing truncating variants in KMT2D were compared to those with missense variants in this gene to those with splice site variants in this gene." (PMID 36276984, 2022).
autoimmune disease (1 paper, 2023). A disorder resulting from loss of function or tissue destruction of an organ or multiple organs, arising from humoral or cellular immune responses of the individual to their own tissue constituents. "Moreover, a clustering of missense mutations in the terminal region of the KMT2D gene might increase the risk for autoimmune diseases, depending either on defective regulatory T-cells (Tregs) generation or intrinsic B tolerance breakage." (PMID 37360370, 2023).
B-cell neoplasm (1 paper, 2025). A group of heterogeneous lymphoid tumors generally expressing one or more B-cell antigens or representing malignant transformations of B-lymphocytes. "Whole-exome sequencing revealed an elevated somatic copy number alteration burden and pathogenic variants in ARID1A, KMT2D, BCL7A, PTPN11, and NUP214, suggesting disruptions in chromatin remodeling, B-cell neoplasm pathogenesis, and oncogenic signaling driving the tumorigenesis." (PMID 41378284, 2025).
breast angiosarcoma (1 paper, 2025). A malignant vascular neoplasm arising from the breast. "Among primary breast angiosarcomas, mutations in PIK3CA and KMT2D are common, with PIK3CA being associated with a worse prognosis in prior studies." (PMID 41301029, 2025).
cervical adenocarcinoma (1 paper, 2026). An adenocarcinoma arising from the cervical epithelium.
Cirrhosis (1 paper, 2021). A chronic disorder of the liver in which liver tissue becomes scarred and is partially replaced by regenerative nodules and fibrotic tissue resulting in loss of liver function.
cold agglutinin disease (1 paper, 2019). Cold agglutinin disease is a type of autoimmune hemolytic anemia defined by the presence of cold autoantibodies (autoantibodies which are active at temperatures below 30B0C). "Genomic studies are limited in these forms, except for recurrent mutations of KMT2D and CARD11 in cold agglutinin disease, which is considered a clonal B-cell lymphoproliferative disorder resulting in AIHA." (PMID 31998632, 2019).
congenital heart malformation (1 paper, 2024). A disease that has its basis in the disruption of heart development. "Through clinical exome sequencing, we performed genetic diagnosis on a newborn with congenital heart malformation and identified a heterozygous mutation in the KMT2D gene, NM_003482.3:c.4195C>T (p.Gln1399*), which has not been reported as a pathogenic mutation before." (PMID 39678395, 2024).
cutaneous squamous cell carcinoma (1 paper, 2024).
cystic hygroma (1 paper, 2019). A benign lymphatic neoplasm usually arising from the neck and characterized by cystic dilation of the lymphatic vessels. "Variants in KMT2D were one of the most frequent diagnostic findings, and these variants were associated with several phenotypes, including multisystem anomalies (PP1843), isolated complex cardiac defects (PP1864), and fetal hydrops and cystic hygroma (PP1573)." (PMID 30712880, 2019).
Endometrioid carcinomas (1 paper, 2020). "Endometrioid carcinomas, which originate from the same tissue as OCCC, have been shown to frequently harbor mutations in genes such as CTNNB1 (42% of samples), KMT2D (31%), KMT2B (19%), and PIK3R1 (19%)." (PMID 33153119, 2020).
endometrioid ovarian cancers (1 paper, 2025).
esophageal tumors (1 paper, 2021). "Moreover, all KMT2D mutations examined in esophageal tumors was clonal." (PMID 34194626, 2021).
familial hyperinsulinemic hypoglycemia (1 paper, 2020). "KMT2D-related Kabuki syndrome 1 (OMIM: 147920) and ABCC8-related familial hyperinsulinemic hypoglycemia (OMIM 256450) were two of the most common disorders." (PMID 33240318, 2020).
female infertility (1 paper, 2024). Diminished or absent ability of a female to achieve conception. "Consistent with expression data from patient samples, our mouse model revealed that deletion of Kmt2d in uterus led to female infertility due to implantation failure, but knockout of Kmt2c did not." (PMID 39117610, 2024).
heart failure (1 paper, 2023). Inability of the heart to pump blood at an adequate rate to meet tissue metabolic requirements. "Our study indicates that KMT2D depletion in both cardiomyocytes and ECs attenuates angiogenesis and that loss of KMT2D exacerbates heart failure after MI in mice." (PMID 36947365, 2023). "Using Kmt2d-cKO mice, we further clarified that KMT2D is indispensable in the heart, because the loss of KMT2D exacerbated heart failure and increases the rate of cardiomyocytes apoptosis after MI." (PMID 36947365, 2023).
Hepatic steatosis (1 paper, 2023). Steatosis is a term used to denote lipid accumulation within hepatocytes. "Another critical epigenetic regulator of overnutrition-induced hepatic steatosis is the histone H3 lysine 4 methyltransferase mixed-lineage leukaemia 4 (KMT2D; also known as MLL4)." (PMID 36650321, 2023).
histiocytic sarcoma (1 paper, 2023). An aggressive malignant neoplasm with a poor response to therapy, usually presenting as stage III/IV disease. "However, soft tissue sarcoma also harbors more mutations in chromatin modeler genes (e.g., ARID1A and KMT2D) and the neurotrophic tyrosine kinase receptor gene NTR1, as well as higher panel-specific TMB, compared to histiocytic sarcoma." (PMID 37414794, 2023).
Infertility (1 paper, 2024). "Further study revealed that uterine deletion of Kmt2d in mice caused infertility due to implantation failure." (PMID 39117610, 2024). "Ablation of Kmt2d in murine uterus resulted in infertility due to implantation failure, accompanied by uterine gland hypo-development and abnormal stratified differentiation of the uterine epithelium." (PMID 39117610, 2024). "Administration of leukemia inhibitory factor protein, which is expressed in uterine glands and is essential for implantation, did not rescue implantation failure in Kmt2d knockout mice, suggesting that infertility was not solely due to uterine gland dysfunction." (PMID 39117610, 2024).
Insulin resistance (1 paper, 2018). Increased resistance towards insulin, that is, diminished effectiveness of insulin in reducing blood glucose levels. "Although the precise molecular mechanism underlying KMT2D’s impact on metabolism remains to be uncovered and might differ from disease to disease, it has been shown before that mutations in Mll2 result in insulin resistance and impaired glucose tolerance in mice." (PMID 30279699, 2018).
invasive breast carcinoma (1 paper, 2019). A carcinoma that infiltrates the breast parenchyma. "We identified KMT2D, SETD1A and SETD2, included in the lysine methyltransferase activity function, as linked with poor prognosis in invasive breast cancer." (PMID 30990809, 2019).
laryngeal squamous cell carcinoma (1 paper, 2025). A squamous cell carcinoma that arises from the larynx.